BDNF (brain derived neurotrophic factor)
Diseases named in the same sentence as BDNF in open-access papers (continued):
Sharing a sentence is not in itself a finding about the gene and the disease.
Down syndrome (18 papers, 2010 to 2026). "In Down's syndrome, overinhibition and a reduced BDNF expression have been implicated in the reduction of dendritic complexity." (PMID 37587917, 2023). "Hyperactivated mTOR signaling in Down’s syndrome mouse neurons augments dendritic translation and brain-derived neurotrophic factor (BDNF) synthesis, resulting in insensitivity to extracellular BDNF signaling." (PMID 36910151, 2023). "There is evidence in mouse models of Down syndrome that SSRIs stimulate brain-derived neurotrophic factor (BDNF) when given early in development." (PMID 31780970, 2019). "The aim of our study is to investigate the relationship between age and brain-derived neurotrophic factor (BDNF) levels in Down Syndrome (DS)." (PMID 20181009, 2010). "However, previous findings showed that in the hippocampus of wild-type mice, P021 does not cause an increase in BDNF levels, and consequently does not affect behavior, in contrast with findings observed in a mouse model of Down syndrome." (PMID 39592934, 2024). "Quite interestingly, a significant difference emerges in the BDNF serum levels between DS and control groups in the ANOVA for the Down Syndrome condition." (PMID 32280719, 2020). "In a mouse model of Down syndrome, the accelerated death of hippocampal neurons is not rescued by exogenous BDNF delivery but instead by restoring the physiological levels of TrkB.T1." (PMID 31948437, 2020). "Furthermore, these ages related differences in serum levels of BDNF, IL-6 and MCP-1 are not statistically significative in control subjects, while in Down's syndrome patients are much more evident and statistically significative." (PMID 20181009, 2010).
hearing loss (18 papers, 2011 to 2025). "The findings of this study shed light on several key aspects of neurotrophic factor therapy for hearing loss induced by ototoxic insults, specifically focusing on the role of BDNF and its potential efficacy in mitigating cochlear damage induced by CDDP." (PMID 40583761, 2025). "A wide number of studies have revealed that BDNF and NT-3 are the most common neurotrophic factors used in animal models of hearing loss." (PMID 37109038, 2023). "Wissel and co-workers demonstrated, by immunohistochemical studies of cochlear sections, a differential expression of BDNF and TrkB in SGNs in normal hearing and in rats with hearing loss treated with neomycin." (PMID 37109038, 2023). "In the present study, we investigated the protection of the organ of Corti by BDNF in an animal model of sensorineural hearing loss." (PMID 35053747, 2021). "Supraparticles have already been used to deliver the developmental neurotrophin, brain-derived neurotrophic factor (BDNF), to the inner ear of a hearing loss guinea pig model." (PMID 32733204, 2020). "Within this group, the patients with profound hearing loss expressed a significantly reduced proteome, when considering proteins regulated by BDNF." (PMID 30971872, 2019). "The unique profile of M3 revealed here warrants further investigation, and the broad activity profile of BDNF observed underpins its continued development as a hearing loss therapeutic." (PMID 31671109, 2019). "This demonstrates that NT-3 can pass the blood-labyrinth-barrier (in contrast to BDNF that has a larger molecular size), and this led us to test the effect of NT-3 in our mouse model of meningitis-associated hearing loss." (PMID 21261959, 2011). "As expected, both NT3 and BDNF displayed beneficial therapeutic effects on repair and/or regeneration of damaged afferent fibers of SGNs and IHC synapses, as already shown in noise- or ototoxin-induced hearing loss in vivo." (PMID 38397748, 2024). "Additionally, BDNF has been shown to promote neuronal survival of afferent cochlear neurons in several animal models of hearing loss." (PMID 37109038, 2023). "Several animal studies have shown that treatment with BDNF or NT-3 has beneficial effects on SGN afferent fibers, synapses, and hearing function after noise or ototoxin-induced hearing loss." (PMID 31671109, 2019). "Taken together, these data suggest that exogenous application of BDNF, NT-3 and M3 may be a means to facilitate reconnection of type 1 cochlear afferent fibers with inner hair cells and provide a therapeutic strategy for addressing synaptopathy that has been associated with hidden hearing loss." (PMID 31671109, 2019). "Gene therapy with neurotrophic factor genes such as NT3, BDNF or GDNF resulted in long-term protection of SGNs after noise-induced, ototoxic, or hereditary hearing loss." (PMID 25276779, 2014). "As most of our participants were middle-aged and had mostly no-to-mild hearing impairment, the observed association might potentially be related to compensatory neuroplasticity alterations in certain brain regions and associated increased BDNF levels." (PMID 35250657, 2022). "We investigated whether treatment with brain-derived neurotrophic factor (BDNF), which is known to protect spiral ganglion cells (SGCs), could also protect hair cells (HCs) and supporting cells (SCs) in the organ of Corti of a guinea pig model of sensorineural hearing loss." (PMID 35053747, 2021).
irritable bowel syndrome (18 papers, 2014 to 2025). Irritable bowel syndrome (IBS) is a chronic functional condition of the lower gastrointestinal (GI) tract characterized by abdominal pain or discomfort and disordered bowel habit (diarrhea, constipation, or fluctuation between the two). "Alterations in the expression of BDNF in the gastrointestinal tract and brain are associated with impaired intestinal motility, psychiatric disorders, irritable bowel syndrome, and antibiotic-induced dysbiosis." (PMID 33993886, 2021). "In patients with irritable bowel syndrome, increased expression of BDNF has been associated with higher abdominal pain scores." (PMID 31010055, 2019). "It has been reported that irritable bowel syndrome was associated with the up-regulation of BDNF in the intestinal mucosa and that colonic BDNF expression correlated with the severity of abdominal pain." (PMID 25383981, 2014). "In the colon, BDNF preserves mucosal integrity and plays a crucial role in the pain associated with irritable bowel syndrome (IBS)." (PMID 39596179, 2024). "The over-expressed colonic brain-derived neurotrophic factor (BDNF) has been reported to be associated with abdominal pain in patients with irritable bowel syndrome (IBS)." (PMID 26837784, 2016). "In another pathophysiological condition, in irritable bowel syndrome, BDNF also makes a significant contribution, since increased expression of BDNF in colonic mucosa, contributes to the visceral hyperalgesia." (PMID 29904026, 2018). "In the colonic mucosa of patients with irritable bowel syndrome, increased BDNF expression was correlated with visceral hyperalgesia and increased abdominal pain scores." (PMID 29246003, 2017). "Moreover, IL-1β also appears to promote BDNF release in enteric glial cells in subjects with irritable bowel syndrome; and levels of this cytokine have also been correlated with the severity and frequency of abdominal pain in this context." (PMID 34638711, 2021). "Several studies have implied a role of brain-derived neurotrophic factor (BDNF) in abdominal pain modulation in irritable bowel syndrome (IBS)." (PMID 33519536, 2020). "For irritable bowel syndrome (IBS), curcumin normalizes neurotransmitter, BDNF and p-CREB levels in the hippocampus and colon." (PMID 40918536, 2025).
anorexia nervosa (17 papers, 2008 to 2025). A disorder most often seen in adolescent females characterized by a refusal to maintain a minimally normal body weight, an intense fear of gaining weight, a disturbance in body image, and, in postmenarcheal females, the development of amenorrhea. "This review explores the intricate relationship between BDNF and anorexia nervosa (AN), a complex psychiatric disorder characterized by disordered eating behaviors and severe medical consequences." (PMID 39203753, 2024). "This study investigated for the first time the role of the BDNF Val66Met allelic substitution in a rat model of anorexia nervosa (AN), known as activity-based anorexia (ABA)." (PMID 35625351, 2022). "Brain-derived neurotrophic factor (BDNF), a neurotrophin involved in the regulation of food intake and body weight, has been implicated in the development and maintenance of Anorexia nervosa (AN)." (PMID 33572701, 2021). "BDNF is thought to exert an anorexigenic effect, but it remains unclear how serum BDNF levels correlate with the onset and course of anorexia nervosa." (PMID 36831706, 2023). "A significant amount of research links BDNF to anorexia nervosa." (PMID 36831706, 2023). "Interestingly, adult anorexia nervosa patients reportedly display lower than normal serum levels of BDNF while obese adults present higher than normal serum BDNF levels." (PMID 18382675, 2008). "Our team found a negative correlation between the BDNF serum level and reward-dependence (RD) in adolescent girls diagnosed with anorexia nervosa." (PMID 40002454, 2025). "Brain-derived neurotrophic factor (BDNF) is abundantly expressed in brain regions involved in both homeostatic and hedonic feeding, and it circulates at reduced levels in patients with anorexia nervosa (AN)." (PMID 35625351, 2022). "Thus, the study aimed to measure the serum level of BDNF and its receptor—tropomyosin-related kinase B (TrkB) and OXY in the malnourished anorexia nervosa patients and following partial weight-recovery." (PMID 32184739, 2019).
Ataxia (17 papers, 2011 to 2024). Ataxia refers to impaired coordination of voluntary muscle movement. "One of the signalling pathways implicated in ataxia is that of brain-derived neurotrophic factor (BDNF) through its high-affinity receptor TrkB." (PMID 39194574, 2024). "Studies involving mice lacking BDNF have revealed significant deficiencies in coordination and balance (ataxia) and sensory deficits, underlining the critical role of BDNF in these processes." (PMID 38892438, 2024). "Antisense oligonucleotides targeting ATXN2 was a potential therapy for spinocerebellar ataxia, whose pathogenic mechanism associates with the BDNF expression reduction." (PMID 37072935, 2023). "The pathogenic mechanism of spinocerebellar ataxia associates with reduction in BDNF mRNA expression and abnormal localization of BDNF protein." (PMID 37072935, 2023). "Antisense oligonucleotides (ASOs) targeting ATXN2 was a potential therapy for spinocerebellar ataxia, whose pathogenic mechanism associates with reduced BDNF expression." (PMID 37072935, 2023). "Specifically, we examined whether dysfunctional BDNF–TrkB signalling in a specific subset of cerebellar GCs is sufficient to cause ataxia in mice." (PMID 39194574, 2024). "Altogether, these data indicate that the disruption of BDNF–TrkB signalling in a specific subset of GCs derived from enkephalinergic precursors is sufficient to produce ataxia symptoms in mice." (PMID 39194574, 2024). "Reduced BDNF expression in the SCA6 cerebellum and reduced BDNF protein in the SCA1 cerebellum implicate BDNF–TrkB signalling in the pathophysiology of these ataxia disorders." (PMID 39194574, 2024). "This study shows that ataxia can be induced by the depletion of BDNF–TrkB signalling in a specific group of cerebellar GCs." (PMID 39194574, 2024). "In spinocerebellar ataxia 6 (SCA6), for example, decreased BDNF–TrkB signalling appears to contribute to PC dysfunction and ataxia." (PMID 39194574, 2024). "Our findings support this view by showing that disrupted BDNF–TrkB signalling in just a subset of GCs is sufficient to initiate ataxia symptoms." (PMID 39194574, 2024). "Decreased cerebellar BDNF–TrkB signalling is a feature of some cerebellar ataxias such as SCA6, Friedreich’s Ataxia, and SCA1, which includes evidence of decreased BDNF levels in the GC layer of SCA6 mice." (PMID 39194574, 2024). "Stg mouse is a mutant mouse model with cerebellar ataxia, BDNF is significantly reduced in the cerebellum other than other brain regions of the mouse." (PMID 35814950, 2022). "Our study found several novel lines of evidence linking BDNF-TrkB pathway with exercise-induced neuroprotection in the cerebellum of the spastic Han Wistar rat, a model of ataxia." (PMID 25710032, 2015). "The potential beneficial effect of BDNF in ataxia has been previously proven in an ataxic mouse model, where inoculation of BDNF transgene into stargazer mutant mice improved their behavior test." (PMID 23671637, 2013). "To investigate whether abnormal BDNF–TrkB signalling in a subset of GCs is sufficient to evoke ataxia, we used TrkbPenk-KO mice carrying Ntrk2 deletion in their enkephalinergic precursor cells." (PMID 39194574, 2024). "This study investigated whether dysfunctional BDNF–TrkB signalling restricted to a specific subset of cerebellar GCs can generate ataxia in mice." (PMID 39194574, 2024). "Thus, BDNF–TrkB signalling is reduced in cerebellar GCs in certain ataxia disorders, potentially contributing to ataxia symptoms." (PMID 39194574, 2024). "Notably, Ntrk2 mutant (Wnt1Cre;fBZ/fBZ) mice were ataxic, as seen from the paw print and accelerated rotarod tests, supporting the idea that dysfunctional BDNF–TrkB signalling can contribute to ataxia symptoms." (PMID 39194574, 2024). "In this study, we investigated whether dysfunctional BDNF–TrkB signalling restricted to a specific subpopulation of cerebellar GCs is sufficient to evoke ataxia symptoms in mice." (PMID 39194574, 2024).
Ataxia (continued). "The findings from this study may aid in developing symptomatic treatments for ataxia (imbalance) in disorders presenting with dysfunctional cerebellar BDNF–TrkB signalling, such as SCA6 and SCA1." (PMID 39194574, 2024). "The suppression of BDNF expression is a potentially momentous phenomenon in many neurodegenerative disorders caused by abnormal expansion of tri-nucleotide (CAG) repeats encoding polyglutamine (polyQ), such as spinocerebellar ataxias (SCAs)." (PMID 38397008, 2024). "In addition to cerebellar ataxias, BDNF plays crucial neuroprotective and immunomodulatory roles in other pathological situations." (PMID 38397008, 2024). "Several lines of evidence have suggested that an enhancement of the cerebellar BDNF pathway may provide therapeutic strategies for the treatment of spinocerebellar ataxias." (PMID 38397008, 2024). "First, this study only included persons with spastic CP, and it is unclear how the BDNF genotype may affect the motor-related oscillatory activity in persons with other types of CP (e.g., athetoid, ataxia, mixed)." (PMID 35447966, 2022). "Therefore, dysfunctional BDNF–TrkB signalling in GCs may contribute to the ataxia symptom in disorders such as SCA1 and SCA6." (PMID 39194574, 2024). "Thus, the question is whether dysfunctional BDNF–TrkB signalling in a subpopulation of cerebellar GCs can generate ataxia in mice." (PMID 39194574, 2024). "Previous work in our lab shows that around disease onset, BDNF-TrkB signaling contributes to SCA6, and that activating this signaling pathway can reverse ataxia at early disease stages." (PMID 38286873, 2024). "Moreover, mice with a targeted gene deletion of BDNF show decreased TrkB signaling in GrCs and PCs and exhibit a wide-based ataxic gait, indicating that the impairment of BDNF-TrkB signaling pathway may not only result from polyQ expansion but also contribute to the onset of ataxia symptoms." (PMID 38397008, 2024). "Therefore, dysfunctional BDNF–TrkB signalling in GCs could interfere with PC function and contribute to the ataxia symptoms in SCA6 and other ataxias where BDNF–TrkB signalling is abnormal." (PMID 39194574, 2024). "However, we found that as disease progresses, BDNF-TrkB signaling is no longer sufficient to reverse ataxia, suggesting that other mechanisms likely contribute to SCA6 as disease progresses." (PMID 38286873, 2024). "As a decrease in cerebellar BDNF–TrkB signalling has been observed in spinocerebellar ataxias, including SCA1 and SCA6, our findings suggest that the dysfunction of GCs may contribute to the development of ataxia symptoms of these disorders." (PMID 39194574, 2024). "Other ataxias like SCA1 also have reduced BDNF protein levels, so it would be interesting to determine whether early endosome deficits could contribute to disrupted BDNF signaling in other ataxias." (PMID 38084749, 2023). "Finally, in a mouse ataxia model, EE was found to reduce behavioral disinhibition but failed to change motor performance and cerebellar BDNF expression." (PMID 35565093, 2022). "Complicated SPG-30 may include cerebellar dysfunction typically characterized by ataxias as cerebellar neurons would be affected similarly to other cell types by the lack of BDNF." (PMID 31616253, 2019).